NOS2P2 (nitric oxide synthase 2 pseudogene 2)
Synonyms: formerly NOS2B
Gene: Transcribed unprocessed pseudogene on chromosome 17 (18,497,567 to 18,503,282, reverse strand). Ensembl gene ENSG00000167494.
Diseases named in the same sentence as NOS2P2 in open-access papers:
NOS2P2 is named in the same sentence as 10 diseases in open-access papers, as found by Europe PMC text mining. Sharing a sentence is not in itself a finding about the gene and the disease.
NOS2P2 shares sentences with these, for which no sentence is quoted: infection (3 papers); atherosclerosis (1); cardiovascular diseases (1); diabetes (1); endothelial dysfunction (1); glioma (1); Hypertension (1); Insulin resistance (1); Salmonella Infections (1); tumor (1).